NKPD1 (NTPase KAP family P-loop domain containing 1)
Synonyms: FLJ33600
Tractability: Antibody: UniProt predicts a signal peptide or a membrane-spanning region.
Gene: Protein-coding gene on chromosome 19 (45,149,744 to 45,160,982, reverse strand). Ensembl gene ENSG00000179846.
Subcellular location: Membrane
Subcellular location (Human Protein Atlas): Cytosol; Plasma membrane; Nucleoplasm; Vesicles
Gene Ontology:
Cellular component: membrane
Genetic constraint (gnomAD): Loss-of-function variants: 37 observed, 27.96 expected, observed/expected ratio (o/e) 1.32, 90% interval 1.02 to 1.73. The synonymous counts are far from expectation, so gnomAD's model fits this gene poorly and the ratio says little. Missense variants: 1,110 observed, 973.4 expected, observed/expected ratio (o/e) 1.14, 90% interval 1.09 to 1.2. Synonymous variants: 552 observed, 433.02 expected, observed/expected ratio (o/e) 1.27, 90% interval 1.19 to 1.37.
Homologues: Orthologues: guinea pig NKPD1 (78% identical), mouse Nkpd1 (78% identical), pig NKPD1 (78% identical), rat Nkpd1 (77% identical), macaque NKPD1 (77% identical), chimpanzee NKPD1 (73% identical), dog NKPD1 (62% identical), tropical clawed frog nkpd1 (33% identical), zebrafish nkpd1 (24% identical).
Diseases named in the same sentence as NKPD1 in open-access papers:
NKPD1 is named in the same sentence as 2 diseases in open-access papers, as found by Europe PMC text mining. Sharing a sentence is not in itself a finding about the gene and the disease. The quoted sentences say what the papers report.
Alzheimer disease (1 paper, 2023). A progressive, neurodegenerative disease characterized by loss of function and death of nerve cells in several areas of the brain leading to loss of cognitive function such as memory and language. "Among the top 20 associated genes, the gene-set enrichment analysis showed that the GWAS catalog gene-set of Alzheimer’s disease or pleiotropy had 4 genes (GEMIN7, MARK4, PPP1R37, and NKPD1) overlapped (p = 1.74 × 10−7, adjusted-p = 3.16 × 10−4)." (PMID 37391420, 2023).
cancer (1 paper, 2022). A tumor composed of atypical neoplastic, often pleomorphic cells that invade other tissues. "The L_cancer patient prognosis features and risk score were calculated as: KNG1 × 0.621 + CYP11A1 × 0.600 + SMPD1 × 1.370 + DAND5 × 0.859 + NKPD1 × 0.721 + RP11-59D5_B.2 × 0.568 + CTD-2184C24.2 × 0.514 + RP11-680F8.3 × 0.517 − RP11-51F16.9 × 0.731 + CTD-2012K14.8 × 0.765." (PMID 36419007, 2022).